PLAC8 (placenta associated 8)
Diseases named in the same sentence as PLAC8 in open-access papers (continued):
Sharing a sentence is not in itself a finding about the gene and the disease.
hepatocellular carcinoma (7 papers, 2005 to 2024). A malignant tumor that arises from hepatocytes. "In hepatocellular carcinoma, PLAC8 is a tumor suppressor regulated by miR-185-5p, and it also suppresses cell proliferation." (PMID 33611659, 2021). "Accumulating evidence have shown that PLAC8 is involved in the participation of cancer processes, including in the hepatocellular carcinoma, nasopharyngeal carcinoma and lung cancer." (PMID 33611659, 2021). "PLAC8 is over-expressed in hepatocellular carcinoma tumours and reduced in Paclitaxel-resistant prostate cancer." (PMID 20459861, 2010). "The detection of BMPR1A was expected to be more sensitive and specific than the detection of PLAC8 gene methylation in patients with hepatocellular carcinoma recurrence, and PLAC8 methylation is expected to be a method that can be used to monitor the recurrence of hepatocellular carcinoma." (PMID 39766341, 2024).
lung carcinoma (7 papers, 2018 to 2024). "Previous studies also showed that PLAC8 promotes lung cancer cell growth by activating the Wnt/ β-Catenin signaling pathway." (PMID 37927794, 2023). "In the in vitro experiments, we transfected PLAC8 into lung cancer cell lines A549 and H 1579 using lentiviral vectors carrying the human PLAC8 gene." (PMID 35497881, 2022). "We performed Western blot and IHC analyses and found that after PLAC8 overexpression, the expression of β-Catenin was increased at both the cellular level (lung cancer cells) and tissue level (lung cancer tissue)." (PMID 35497881, 2022). "As far as we know, this is the first work to establish that the Wnt/β-Catenin signaling pathway (mediated by PLAC8) is involved in the growth of lung cancer cells." (PMID 35497881, 2022). "We examined the expression of Wnt/β-Catenin signaling pathway components in A549 and H838 lung cancer cells following PLAC8 overexpression and PLAC8 silencing to learn more about PLAC8's regulatory route in vivo." (PMID 35497881, 2022). "We initially investigated the expression of PLAC8 in human lung cancer tissue and serum from lung cancer patients and discovered that PLAC8 expression was considerably greater in lung cancer tissue and serum from lung cancer patients than in healthy controls." (PMID 35497881, 2022). "Next, we evaluated serum PLAC8 in 68 patients with lung cancer; the levels were significantly higher than those in healthy controls." (PMID 35497881, 2022). "We also investigated the effect of reduced PLAC8 gene regulation on the viability and proliferation of H838 and H322 lung cancer cell lines in vivo and in vitro." (PMID 35497881, 2022). "PLAC8 expression was elevated in lung cancer tissues and plasma and decreased in plasma after lung tumor resection." (PMID 35497881, 2022). "PLAC8 protein expression in human lung cancer tissues and lung tumor cells of different strains was discovered using immunohistochemistry staining and Western blot, respectively." (PMID 35497881, 2022). "It was determined from these findings that PLAC8 served as an oncogene in an experimental lung cancer model in mice." (PMID 35497881, 2022). "We find that PLAC8 is a key limiting host factor, whose overexpression boosts viral infection in eight different human lung cancer cell lines." (PMID 36124427, 2022). "The results showed that PLAC8 expression was significantly upregulated in the lung tissue from patients with lung cancer, which was consistent with our IHC results for PNCA and Ki-67, known as cancer-related genes in the lung tissue." (PMID 35497881, 2022). "The main significance of the study is that we have found that the PLAC8 promotes lung cancer cell growth by activating the Wnt/β-Catenin signaling pathway." (PMID 35497881, 2022). "In this retrospective analysis, we were able to establish that overexpression of PLAC8 increased the growth of lung cancer cells strongly." (PMID 35497881, 2022). "The PLAC8 expression in lung cancer tissues and in vitro grown lung cancer cells, as well as the involvement of the Wnt/β-Catenin signaling pathway, was investigated in this process." (PMID 35497881, 2022). "Altogether, these experiments confirm and extend our screen results and demonstrate that loss‐of‐function of PLAC8 and SPNS1 specifically impairs viral entry of S‐typed lentiviruses in human lung cancer cells." (PMID 36124427, 2022). "Some researchers showed that endogenous PLAC8 promoted cell proliferation and tumor formation in lung cancer." (PMID 32903581, 2020). "So the KLF4/PLAC8 axis should be a candidate targeted therapy for lung cancer." (PMID 38560274, 2024). "Therefore, the undertaken study indicated that the expression of PLAC8 was upregulated in lung tissue and serum from patients with lung cancer." (PMID 35497881, 2022).
lung carcinoma (continued). "A potential treatment targeting the prognosis of lung cancer patients may be PLAC8 overexpression, which promotes the lung cancer cell proliferation through controlling the Wnt/β-Catenin signaling pathway." (PMID 35497881, 2022). "Previous studies have confirmed that PLAC8 expression is increased in patients with lung cancer." (PMID 35497881, 2022). "We further analyzed the PLAC8 expression in different lung cancer cells." (PMID 35497881, 2022). "PLAC8 knockdown dramatically reduced tumor cell growth, indicating that PLAC8 might be a potential therapy target for lung cancer." (PMID 35497881, 2022). "However, contrary to prior studies, this research found that PLAC8 was significantly expressed in the majority of lung cancer cell lines." (PMID 35497881, 2022). "Also, we found that PLAC8 overexpression promoted the proliferation of lung cancer cells." (PMID 35497881, 2022). "Moreover, serum PLAC8 in patients with lung cancer was significantly reduced after operation." (PMID 35497881, 2022). "Therefore, this study shows that PLAC8 is overexpressed in human lung cancer tissue and serum." (PMID 35497881, 2022). "Placental specific 8 (PLAC8) was positively correlated with tumor size, histological grade, TNM stage, and poor prognosis of lung cancer." (PMID 38560274, 2024). "In lung cancer, KLF4 negatively regulated placenta-specific 8 (PLAC8) expression by binding to the promoter of PLAC8, which suppressed cell proliferation and apoptosis." (PMID 32756012, 2020). "In the current study, both the clinical implications and biological effects of PLAC8 in lung cancer (LC) progression were investigated, and we identified and described the novel Krüppel-like factor 4 (KLF4)/PLAC8 regulatory pathway in cancer progression." (PMID 29789534, 2018).
pancreatic cancer (7 papers, 2018 to 2023). "Additionally, deficiency of PLAC8 in mouse models of pancreatic cancer inhibits tumor formation." (PMID 37927794, 2023). "Inhibiting PLAC8 expression significantly inhibits pancreatic cancer cell growth by affecting cell-cycle progression and modifying key cell-cycle regulators." (PMID 37927794, 2023). "Recent evidence suggests that in pancreatic cancer cells, PLAC8 localizes to the inner face of the plasma membrane and interacts with specific membranous structures in a stable manner." (PMID 37927794, 2023). "Placenta-specific 8 (Plac8) was upregulated 2.9-fold at P0, and is also involved in pancreatic cancer progression." (PMID 36232358, 2022). "Mac5 was characterized by the expression of Chil3, placenta associated 8 (Plac8) and Ly6c2, which was recently reported in KPC pancreatic cancer mouse model." (PMID 36451853, 2022). "Accordingly, it was identified that some localized proteins, like the protein placenta-specific 8 (PLAC8, Onzin), are related to the pancreatic tumour progression." (PMID 35180880, 2022). "PLAC8 has been shown to promote autophagosome‐lysosome fusion by activating pro‐survival function of autophagy in pancreatic cancer." (PMID 34117724, 2021). "PLAC8 also plays a role in autophagosome‐lysosome fusion by initiating oncogenic autophagy in pancreatic cancer." (PMID 34117724, 2021). "In cancer cells, PLAC8 induced epithelial‐mesenchymal transition, and cell cycle was reported to be regulated by PLAC8 in pancreatic cancer cells." (PMID 34117724, 2021). "For example, PLAC8 was critical to human prostate cancer and pancreatic cancer growth and metastasis according to previous studies." (PMID 29789534, 2018). "Therefore, from a practical standpoint, we propose that PLAC8 holds promise as a potential treatment target for pancreatic cancer, providing a foundation and new insights for targeted therapy in pancreatic cancer patients." (PMID 37927794, 2023). "Besides, several studies have demonstrated the role of PLAC8 in the regulation of autophagy during pancreatic cancer progression and prostate carcinogenesis." (PMID 34117724, 2021).
COVID-19 (6 papers, 2021 to 2025). A disease caused by infection with severe acute respiratory syndrome coronavirus 2. "To evaluate this, first, we leveraged our pre-infection samples and tested whether PLAC8 expression in CD14 monocytes prior to infection was associated with subsequent peak illness severity during COVID-19." (PMID 40532694, 2025). "We therefore considered whether the association between increased expression and severe COVID-19 reflected a causal role for PLAC8 in the pathogenesis of COVID-19 severity mediated through increased viral entry." (PMID 40532694, 2025). "Third, we performed Mendelian randomization (MR), an analytical technique that leverages naturally occurring genetic variation to evaluate whether PLAC8 gene expression plays a causal role in COVID-19 severity." (PMID 40532694, 2025). "These lines of data do not support a role for PLAC8 gene expression as a causal factor in COVID-19 severity." (PMID 40532694, 2025). "Interestingly, scRNA-seq unveiled a cluster of immature CD14+ monocytes, with low HLA-DR and expressing MPO, PLAC8, and IL1R2, in the blood of COVID-19 patients and similar cells were reported in sepsis." (PMID 33674591, 2021).
Obesity (6 papers, 2012 to 2022). Accumulation of substantial excess body fat. "This preliminary study confirms the association of SPE with obesity and suggests higher expression of PLAC8 mRNA and protein in placentas from preeclampsia." (PMID 35252239, 2022). "In mice, genetic inactivation of PLAC8 is associated with cold intolerance, late-onset obesity, abnormal morphology, and impaired brown adipocyte function." (PMID 34573572, 2021). "Consistent with previous reports, obesity enhanced the proportion of Itgax+ (encoding CD11c) and Cd9+ ATMs (cluster 0) and Plac8+ monocytes (cluster 4) and reduced the proportion of Lyve1+ and Cd163+ ATMs (cluster 1) and Lyz1+ monocytes." (PMID 34676827, 2021). "COQ2 (coenzyme Q2) and PLAC8 (placenta-specific 8) are candidate genes for the onset of type 2 diabetes associated with obesity in rats." (PMID 31940795, 2020). "PLAC8 is implicated in diseases such as obesity, type 2 diabetes, and GD." (PMID 32028606, 2020). "Thus, it is possible that sustained PLAC8 overexpression could play a central role in the pathophysiological association between obesity and preeclampsia, maintaining the expression of leptin." (PMID 35252239, 2022). "The PLAC8 gene is directly involved in obesity, the placental preimplantation process, and diabetes, making it a good candidate to study in preeclampsia." (PMID 35252239, 2022). "Another identification strategy has been the evaluation of genes related to physiological processes common to preeclampsia and obesity, including the PLAC8 gene (placenta-specific 8)." (PMID 35252239, 2022). "These preliminary results encourage conducting basic studies to clearly identify the interrelationship between PLAC8 and LEPTIN and its involvement in preeclampsia and the associated obesity." (PMID 35252239, 2022). "In vivo, however, Plac8 is dispensable for the formation of white adipocytes but its absence leads to obesity with apparently fewer but greatly enlarged adipocytes." (PMID 23155406, 2012). "In mice, Plac8 is expressed both in white and brown adipose tissues and we previously showed that Plac8−/− mice develop late-onset obesity, with abnormal brown fat differentiation and reduced thermogenic capacity." (PMID 23155406, 2012). "Genes associated with pathophysiological events common to preeclampsia and obesity, such as PLAC8, remain to be studied; therefore, the aim of the present study was to evaluate this gene in the placentas of women affected with preeclampsia and healthy pregnant women." (PMID 35252239, 2022). "Over time, these mice develop obesity for reasons that may be related to defects in thermogenesis and, because Plac8 is also expressed in white adipocyte, to a defect in this tissue homeostasis." (PMID 23155406, 2012). "Mice with genetic inactivation of Plac8 develop late-onset obesity." (PMID 23155406, 2012). "Because the PLAC8 gene is relevant for placental implantation processes and adipogenesis, the aim of this study was to comparatively evaluate PLAC8 in the placentas of Mexican women with and without preeclampsia and obesity." (PMID 35252239, 2022).
prostate carcinoma (5 papers, 2010 to 2025). A carcinoma that arises from epithelial cells of the prostate gland. "In addition, the expression of RBP4 and PLAC8, which were suggested to be associated with prostate cancer cell growth in vitro, was increased in remaining prostate cancer cells in bone." (PMID 23708710, 2013). "In the present study, we demonstrated that OPG reduces osteolysis and cancer cell growth in a mouse model of bone metastasis and that expression of RBP4 and PLAC8, which were suggested to be associated with prostate cancer cell growth in vitro, was increased in maintained prostate cancer cells." (PMID 23708710, 2013). "PLAC8 promotes the growth of tumor cells in prostate cancer cells but significantly inhibits the growth of tumor cells in hepatocellular carcinoma." (PMID 34627411, 2021). "Contrary to the increased cell growth reported in pancreatic and prostate cancer following PLAC8‐induced autophagy, our data strongly suggest that PLAC8 suppresses autophagy and that this leads to increase the cell growth in NPC cells." (PMID 32468683, 2020). "Previous reports have indicated that inhibition of PLAC8 impairs tumour proliferation in pancreatic and prostate cancers by suppressing autophagy." (PMID 32468683, 2020). "PLAC8, as an oncogene, promotes colorectal and prostate cancer cell growth." (PMID 34627411, 2021). "RBP4 and PLAC8 may become new therapeutic targets for prostate cancer bone metastasis, to be used in combination with therapies that inhibit the OPG/RANKL/RANK pathway." (PMID 23708710, 2013). "Since the expression of RBP4 and PLAC8 were increased in tumor cells in PC3-GFP/PC3-OPG-injected mice compared to controls, RBP4 and PLAC8 may be acting as survival factors in prostate cancer cells when osteolytic tumor growth is inhibited by OPG." (PMID 23708710, 2013). "Additionally, specifically targeting PLAC8 may affect prostate carcinogenesis in humans, and PLAC8 activation may be used as a biomarker for the early detection of prostate cancer in cadmium-exposed populations." (PMID 34627411, 2021). "Thus, RBP4 and PLAC8 may become new therapeutic targets for prostate cancer bone metastasis, in combination with OPG/RANKL/RANK pathway inhibition." (PMID 23708710, 2013). "PLAC8 not only promotes EMT progression but is also involved in cancer metastasis, such as bone metastasis in prostate cancer cells and lung metastasis in colorectal cancer cells in vivo." (PMID 34627411, 2021).
colorectal cancer (4 papers, 2019 to 2022). A primary or metastatic malignant neoplasm that affects the colon or rectum. "And Id1 gene which can activate the Wnt/β-catenin and Shh signaling pathways promote PLAC8 expression and then maintains cell stemness in colorectal cancer." (PMID 34627411, 2021). "Higher PLAC8 expression is found in the sphere-forming colorectal cancer cells than in colorectal cancer cells." (PMID 34627411, 2021). "Interestingly, PLAC8 decreases E-cadherin expression but increases P-cadherin and vimentin expression; however, the level of N-cadherin is stable in colorectal cancer cells." (PMID 34627411, 2021). "And butyrate reduced the expression of PLAC8 in colorectal cancer cells." (PMID 34627411, 2021). "The MultiOmyxTM platform has been used to evaluate the epithelial-to-mesenchymal transition in medullary colorectal cancer tissue where coexpression of CK, CDH3, VIM, and Cyt-PLAC8 provided evidence that excess PLAC8 is involved in the epithelial-to-mesenchymal transition." (PMID 30791580, 2019).
nasopharyngeal carcinoma (4 papers, 2019 to 2021). A carcinoma arising from the nasopharyngeal epithelium. "We therefore wondered, whether loss of PLAC8 function might have similar effects in nasopharyngeal cancer cells." (PMID 32468683, 2020). "In nasopharyngeal carcinoma cells, knockout of PLAC8 radiosensitizes nasopharyngeal carcinoma cells by activating the PI3K/AKT/GSK3β pathway." (PMID 34627411, 2021). "PLAC8 inhibits autophagy via the AKT/mTOR pathway in nasopharyngeal carcinoma cells." (PMID 34627411, 2021). "However, PLAC8 promotes the carcinogenesis and EMT of nasopharyngeal carcinoma cells via the TGF-β/Smad pathway." (PMID 33611659, 2021). "Furthermore, in nasopharyngeal carcinoma, PLAC8 contributes to radioresistance by inhibiting the PI3K/AKT/GSK3β pathway, as knockout of PLAC8 sensitizes nasopharyngeal carcinoma cells to radiation by activating the PI3K/AKT/GSK3β pathway." (PMID 31448883, 2019).